CASP10 (caspase 10)
Diseases named in the same sentence as CASP10 in open-access papers (continued):
Sharing a sentence is not in itself a finding about the gene and the disease.
influenza (1 paper, 2021). An acute viral infection of the respiratory tract, occurring in isolated cases, in epidemics, or in pandemics; it is caused by serologically different strains of viruses (influenzaviruses) designated A, B, and C, has a 3-day incubation period, and usually lasts for 3 to 10 days. "Caspases CASP3, CASP8, CASP10, and FAS associated death domain (FADD) are important for apoptosis which is a pathway downregulated upon influenza vaccination." (PMID 34695164, 2021).
lung adenocarcinoma (1 paper, 2019). A carcinoma that arises from the lung and is characterized by the presence of malignant glandular epithelial cells. "Since elevated levels of ACLY have been reported in lung adenocarcinoma, we next examined the levels of ACLY and caspase-10 in different grades of lung adenocarcinoma." (PMID 31534141, 2019). "Conversely, we found that the levels of caspase-10 were markedly reduced with increasing aggressiveness of lung adenocarcinoma." (PMID 31534141, 2019).
periodic fever syndrome (1 paper, 2024). Fevers of unknown etiology recurring over months or years. "However, the pathogenicity of CASP10 variants was debated since its initial description: one of the first two reported variants (p.V410I) was discarded as disease-causing by the same authors, since the index patient was discovered to be affected by TNF receptor-associated periodic fever syndrome." (PMID 38704374, 2024).
psoriasis (1 paper, 2019). An autoimmune condition characterized by red, well-delineated plaques with silvery scales that are usually on the extensor surfaces and scalp. "We found that the interaction of CASP10 - CASP1, CASP10- CASP3, CASP10- CASP4, CASP10- CASP9, CASP10- CASP12, CASP8 - CASP3, CASP8 - CASP4, and CASP1 - CASP12 is important for the risk of psoriasis." (PMID 30906769, 2019).
systemic lupus erythematosus (1 paper, 2014). An autoimmune multi-organ disease typically associated with vasculopathy and autoantibody production. "This study aimed to explore the role of apoptosis initiators, caspase-9, caspase-10, mitochondrial anti-viral signaling protein (MAVS), and interferon regulatory factor 7 (pIRF7), in patients with systemic lupus erythematosus (SLE)." (PMID 25370148, 2014).
type II autoimmune lymphoproliferative syndrome (1 paper, 2014). "Mutations in caspase-10 are associated with autoimmune lymphoproliferative syndrome type II, suggesting that caspase-10 is important for the regulation of normal lymphoid cells." (PMID 25061812, 2014). "However, mutations in CASP10 are associated with type II autoimmune lymphoproliferative syndrome suggesting it has a significant role in lymphoid cells." (PMID 25061812, 2014).
cancer (33 papers, 2010 to 2025). A tumor composed of atypical neoplastic, often pleomorphic cells that invade other tissues. "In our study, bio-informatic analyses showed that apoptosis pathways and genes such as CASP10, which encodes caspase-10, were significantly downregulated, as seen in malignant tumors, adding further evidence for the validity of our model." (PMID 36835505, 2023). "Owing to its role in apoptosis, loss-of-function mutations in caspase-10 have been reported in several cancers including non-Hodgkin lymphoma, gastric carcinoma, and non-small cell lung carcinoma." (PMID 31534141, 2019). "Somatic mutations in CASP10, as well as reduced expression levels of this gene, were found to be associated with a number of different human cancers." (PMID 21187902, 2010). "Our findings revealed an antagonistic interaction between cisplatin and high-THC cannabis extract, which could be linked to alterations in gene transcription associated with cell death (BCL2, BAD, caspase 10), DNA repair pathways (Rad52), and cancer pathways related to drug resistance." (PMID 38674023, 2024). "In all instances, Z-VAD-FMK inhibitor decreased the activation of caspase 10, 9, and 3/7 in response to 3b in both cancer cell lines." (PMID 38700244, 2024). "TNFRSF10B has been shown to interact with FADD, caspase 10, and caspase 8 and induced apoptosis in cancer cells." (PMID 35399006, 2022). "Since ACLY has been reported to be critical for cancer cell proliferation and metastasis, we next examined the effect of caspase-10 on ACLY-promoted malignant phenotype." (PMID 31534141, 2019). "Caspase-10 is highly expressed in lymphoid cells and is frequently down regulated in lymphoid cell lines, and other cancers." (PMID 25061812, 2014). "Inspecting this list, we found several genes, such as thymidine phosphorylase (TYMP), apoptosis-related cysteine peptidase (CASP10), and notch 4 (NOTCH4), have been implicated in cancer cells, but most of the gene are novel ones." (PMID 24171174, 2013). "These included sites in genes that encode caspases (CASP8 and CASP10) and the von Hippel-Lindau (VHL) tumor suppressor, which have been implicated in various cancers." (PMID 24183664, 2013). "Caspase-3 and caspase-7 are key effector molecules known to induce apoptosis in variety of cancer cells by amplifying the signal from initiator caspases, such as caspase-8 or caspase-10." (PMID 22363450, 2012). "Similarly, CASP10 was more highly expressed in monocytes, but its expression in malignant tumor cells was minimal, and its spatial distribution lacked overlap with macrophages." (PMID 41201629, 2025). "Next, we examined the expression level of caspase-10, which is a paralog of caspase-8, is also involved in the death receptor pathway of apoptosis and was found in our transcriptomic data to be activated by ActD + Nut3a in various cancer cell lines." (PMID 39068622, 2024). "Collective lines of evidence suggest that DET holds the potential to induce extrinsic apoptosis by upregulating Fas/FasL, TNF/TNF-R1, DR4/5, active caspase-10, -8, -7, -3, and tBid formation in various cancer cells, which needs to be explored further using in vivo cancer models." (PMID 35408483, 2022). "Moreover, there is also the interesting fact that caspase 10 mediates the sensitivity of cancer cells to TRAIL (tumor necrosis factor-related apoptosis-inducing ligand) induced apoptosis." (PMID 36077839, 2022). "The observed inter-species differences in the regulation of CASP10 following infection may therefore be related to differences in the rates of cancer across species." (PMID 21187902, 2010). "As caspase-10 can directly influence histone acetyltransferases or methyltransferases, other caspases might exhibit similar epigenetic control, creating potential new avenues for therapy in cancer and inflammatory diseases." (PMID 40555741, 2025).
cancer (continued). "To complement these data, we investigated the effects of docetaxel on the expression of HIF-1α target genes (Glut1, CA9, LDHA, and BNIP3) involved in the metabolism of cancer cells and pro-apoptotic genes (CASP3, CASP8, and CASP10) in siJNK2-transfected MDA-MB-231 cells under hypoxic conditions." (PMID 27263528, 2016). "TRAIL interaction with DR4 and DR5 transduces the death receptor (extrinsic) and mitochondrial apoptosis signaling pathways through the activation of caspase-8 and caspase-10; therefore, TRAIL is usually regarded as a drug that treats cancer cells through cFLIP." (PMID 25886453, 2015). "Considering that SODD and caspase-10 are frequently over-expressed in ALL, interfering with these proteins may provide a new strategy for the treatment of this and potentially other cancers." (PMID 25061812, 2014). "We therefore used another cell type, i.e., the HeLa carcinoma cell line, which does express endogenous caspase-8 but not caspase-10 as compared to A3 Jurkat cells." (PMID 21049020, 2010). "Specifically, AK2 mediates mitochondrial apoptosis through the formation of an AK2–FADD–caspase 10 complex, whereas NOX4-mediated ROS production induces apoptosis in cancer and normal cells upon stimulation, for instance by incubation with TNF-α, glucose, or anti-cancer drugs." (PMID 31399108, 2019).
tumor (24 papers, 2009 to 2025). "We genotyped 7 potentially functional polymorphisms in CASP3, CASP7, CASP8, CASP9, CASP10 genes in 362 HCC patients of receiving surgical resection of HCC tumor." (PMID 28453560, 2017). "Acquired inactivating mutations of caspase-10 have been identified in tumor cells from patients with solid tumors." (PMID 21103379, 2010). "Inhibition of caspase-10 reduces the expression of cytokines and facilitates apoptosis in tumor cells." (PMID 39726605, 2024). "Taken together, our results demonstrate that caspase-10 downregulates ACLY promoted tumor metastasis." (PMID 31534141, 2019). "We also observed higher number of circulating tumor cells (CTCs) in mice implanted with caspase-10 knockdown cells as compared to control cells." (PMID 31534141, 2019). "The results implied that the tumor apoptosis was induced by the upregulated expression of HtrA2, caspase 6, caspase 7, caspase 10, Gas2, and Lamin A." (PMID 27275821, 2016). "Caspase-10 was also reported to be activated downstream of the mitochondria in cytotoxic drug-induced apoptosis of tumor cells." (PMID 21103379, 2010). "Furthermore, in mouse tumor models, metabolic stress-induced caspase-10 downregulates ACLY levels which results in reduced tumor progression and metastasis." (PMID 31534141, 2019). "Furthermore, increased Ki67 staining in tumor sections, which is indicative of higher proliferation rate, was observed upon caspase-10 knockdown, while simultaneous knockdown of ACLY or GCN5 significantly reduced the extent of staining." (PMID 31534141, 2019). "Thus our findings highlight a key role for caspase-10 in determining cellular metabolic outcomes and epigenetic control of gene expression, with major implications for tumor progression and metastasis." (PMID 31534141, 2019). "Further analysis of tumor cell lysates revealed that protein expression of cleaved caspase 8, a molecule involved in the extrinsic pathway downstream of activated caspase 10 was significantly increased in tumor xenografts treated with simvastatin, compared to saline treated controls (p<0.01)." (PMID 22974127, 2012). "In addition, significant associations were also seen for tumor grade with Fas, FADD, and caspase 10, and for tumor stage with Fas expression." (PMID 19728877, 2009). "However, CASP10 was highly upregulated in the A1M group (based on data from only one tumor), indicating that A1M may activate the perforin/granzyme B pathway." (PMID 37076494, 2023). "Thus, our data hint at the possibility of modulating caspase-10 expression as a therapeutic oncological target; repression of caspase-10 reduces cytokine expression and favors apoptosis, potentially resulting in impaired tumor growth." (PMID 28445729, 2017). "Our data for CD95L demonstrate that caspase-10 shifts the apoptotic cell death response following DISC formation to the activation of NF-κB and cell survival, both beneficial features for tumor cells." (PMID 28445729, 2017). "Caspase-10 protein was expressed at a low level in the cytoplasm of 23/62 (37%) of tumours and not expressed in 39/62 (63%) and did not predict OS (p = 0.732, log rank test) or RFS (p = 0.693, log rank test)." (PMID 25157404, 2014).
infection (8 papers, 2010 to 2025). The state of being infected such as from the introduction of a foreign agent such as serum, vaccine, antigenic substance or organism. "CASP5 expression was also up-regulated in infected samples, while CASP7 and CASP10 expression served as controls that were unaffected by infection status." (PMID 35588457, 2022). "Interestingly, in our experiments, caspase 10 showed significantly decreased expression on the RNA level in both sexes upon infection at 6 hpi." (PMID 40794782, 2025). "Even if the level of JNK is not different before and after the infection, there is a decrease in CASP10 value, encoding for Caspase-10." (PMID 34769246, 2021). "Pro-apoptotic molecules XAF1, BID, cyto c, CASP10, AIFM2, were significantly up-regulated after infection with N-PRRSV, which may induce apoptosis of virus-infected cells." (PMID 20614006, 2010).
hematologic malignancies (1 paper, 2025). "Notably, several drug-gene pairs—including those targeting CASP8, CASP10, KCNQ1, and HSPA8—are not currently approved nor under clinical evaluation for LN, representing investigational candidates with potential for future development in hematologic malignancies." (PMID 40883272, 2025).
CASP10 also shares sentences with these, for which no sentence is quoted: non-Hodgkin lymphoma (3 papers); colon carcinoma (2); triple-negative breast carcinoma (2); acute lymphoblastic leukemia (1); Arthritis (1); atherosclerosis (1); autoimmune disease (1); Autoimmunity (1); basal cell carcinoma (1); cholangiocarcinoma (1); diabetes (1); Ewing sarcoma (1); juvenile idiopathic arthritis (1); keratitis (1); lymphoma (1); meningioma (1); non-melanoma skin carcinoma (1); non-small cell lung carcinoma (1); oncocytic adenoma (1); ovarian carcinoma (1); pituitary adenoma (1); T cell lymphoma (1); teratozoospermia (1); uterine cancer (1).